IL1B (interleukin 1 beta)
Diseases named in the same sentence as IL1B in open-access papers (continued):
Sharing a sentence is not in itself a finding about the gene and the disease.
infection (continued). "Interestingly, endogenous IL-1β secretion as well as IL-1β (p17) maturation and Casp-1 (p20 and p22) cleavage were induced upon the infections of the three viruses, however, HSV-1-mediated induction was attenuated by sh-STING, but SeV- or ZIKV-mediated inductions were not affected by sh-STING." (PMID 32187211, 2020). "Notably, the mRNA levels of Tnf, Il6, Il1b, Cxcl10, and Cxcl5 were significantly increased and that of Il10 decreased in lung tissue from Ppara-/- mice, compared with Ppara+/+ mice, during Mabc infection." (PMID 32155958, 2020). "Furthermore, as previously noted, treatment of chickens with anti-IL-1β antibodies following infection with GM NDV decreased IL-1β level in organs, reduced body temperature and decreased the mortality rate, further confirming an essential role for IL-1β in the virulence of NDV infection." (PMID 32293543, 2020). "As this mechanism, or mechanisms, is still unresolved, global blockade of IL-1β, independent of specific inflammasomes, remains the preferred treatment modality for inflammasomopathies despite patient susceptibility to life-threatening infections." (PMID 32983094, 2020). "However, at 2 days post infection, we observed decreased release of IL-1β." (PMID 32117283, 2020). "However, IL-1β release induced by 212 infection was comparable in wildtype and Nlrp3−/− iBMDMs." (PMID 32111888, 2020). "Moreover, prior research suggests that some variants of virulence factors found in P. gingivalis, such as LPS and fimbriae are recognized by toll-like receptors (TLRs) during infection, subsequently triggering the NF-κB pathway to up-regulate expression of pro-IL-1β and some NLRs, like NLRP3." (PMID 32903638, 2020). "In addition, at 2 h after infection, IL-1β expression induced by P. gulae D049 (type C) infection was significantly higher than that induced by P. gulae ATCC 51700 (type A) or P. gulae D040 (type B) (P < 0.05); a similar trend was observed with respect to COX-2." (PMID 32080231, 2020). "The decrease in IL-1β levels observed in WT-infected mice corroborates the data of altered intestinal permeability through infection, suggesting that ST2 might have a regulatory role of this cytokine and consequently a function in the maintenance of intestinal permeability." (PMID 32353980, 2020). "Therefore, caspase-1 could influence additional pathology during S. aureus craniotomy infection beyond its role in pro-IL-1β processing; however, this possibility remains speculative." (PMID 32290861, 2020). "Interestingly, contrary to what is observed in other mycobacteria, when invading mammary epithelial cells, MAP is able to induce phagosome acidification between 10 and 30 min post infection and IL-1β production in order to attract subepithelial macrophages at the site of infection." (PMID 31939335, 2020). "Also, the identity of oral mucosal monocytes or macrophages that express active IL-1β/IL-6 during an infection is unknown and warrants future studies." (PMID 33240286, 2020). "However, a rechallenge of previously infected Ccr2-/- mice revealed increased bacterial killing (as indicated by a reduction in S. aureus CFU), decreased infiltrating PML, and less skin IL-1β concentrations as compared to naïve counterparts 5 days after (re-)infection." (PMID 32639232, 2020). "However, inhibition of IL-1β may also lead to the exacerbation of infection and delay tissue repair." (PMID 33143375, 2020). "In addition, the patients infected with TM have previously been reported to have higher TNF-α, IL-1β, IL-12, and IL-10 levels in vivo, and the infection of TM enabled the enhancement of the production of cytokines such as TNF-α, IL-1β, IL-6, and IL-12 by stimulating macrophages in vitro." (PMID 33488545, 2020).
infection (continued). "Thus, our study strongly suggests that depending on the severity of challenge, a corresponding amount of IL-1β was strategically released at a critical time point to orchestrate the transition of acute to chronic phase during the process of infection-related inflammation in the brain." (PMID 32070376, 2020). "Importantly, we could retrieve these antiviral CD8+ T cells in the lung parenchyma of mice treated with WT IL-1β or CD8α ALN-1 more than 50 days after the initial infection, illustrating the longevity of these cells." (PMID 32714571, 2020). "Moreover, the observed marked upregulation of IL-1β was also similar to the early inflammatory response to an experimental Fno infection in tilapia, in which Fno stimulated a significantly higher IL-1β expression in the spleens of Nile tilapia at 24–96 h post-infection." (PMID 32260212, 2020). "IL-1β has been reported to modulate various aspects of immune function including the increased expression of adhesion molecules that can promote monocyte/macrophage and neutrophil infiltration to infection sites as well as the induction of CX3CL1/Fractalkine by IECs." (PMID 33194815, 2020). "In addition to being a major stimulator of apoptosis, TNF-α together with IL-1β are proinflammatory cytokines expressed by PBMCs obtained from normal or B. pseudomallei -infected humans stimulated by infection or LPS, or in cells from B. pseudomallei infected mice." (PMID 32835600, 2020). "Interestingly, LRV accounts to increased Il1b expression at early times of infection." (PMID 31754185, 2019). "However, at 6 days after infection we found a significant increase in IL-1β production." (PMID 31031755, 2019). "Further, they allow us to hypothesize that PEGs may block IL-1β secretion by steric hindrance, as inhibition occur also when PEGs are present only during infection and removed for the post-infection phase, but that this does not seem to be the case for cell death." (PMID 31275321, 2019). "Based on this observation, we hypothesized that the process of infection triggers an inflammasome-mediated response but that HCMV-encoded factors expressed by live virus act to inhibit this, resulting in lower secretion of IL-1β." (PMID 30755509, 2019). "It has been shown that PRRSV could activate NLRP3 inflammasome in early stages of infection but induce host's immunosuppression later as measured by determining the levels of pro-IL-1β and procaspase-1 mRNA and the mature IL-1β protein in porcine alveolar macrophages (PAM)." (PMID 30842948, 2019). "Interestingly, in response to Mtb WCL stimulation, TNFα, IL6, IL12p40, and IL1β were produced to a significantly higher extent by BAL cells of cynomolgus macaques already prior to infection, concordant to the pro-inflammatory profile of circulating monocytes in cynomolgus macaques." (PMID 31736945, 2019). "However, the cerebral content of IL-1α and IL-1β, which contribute to a wide range of neurodegenerative conditions as well as acute and chronic neuroinflammatory processes, differed between both infection groups." (PMID 31315623, 2019). "Indeed, while all inhibitors apart from probucol dose-dependently decreased IL-1β release upon nga(G330D) infection, secretion upon ATP-driven inflammasome activation was reduced by glyburide, DIDS and probucol, unaffected by BLT-4 and increased in the presence of vanadate." (PMID 31275321, 2019). "Therefore, minor differences between PC and DFM birds in terms of IFN-γ and IL-1β mRNA levels might be related to the time of sampling, severity of infection, or probiotic type and dose." (PMID 31921920, 2019). "rBCG-DisA infection could induce IL-1β mRNA upregulation as c-di-AMP did compared with BCG group." (PMID 31333655, 2019). "However, the role of this cytokine in GAS infection is complex; in a forward genetics screen using a panel of intercrossed mice (C57BL/6xDBA/2J), increased susceptibility to GAS and enhanced bacterial growth correlated with increased IL-1β levels during infection." (PMID 31275321, 2019).
infection (continued). "In addition, IL-1β and IL-18 are IL-1 family members, could contribute to the development of T cell responses, and shape adaptive immune response during infection." (PMID 30105037, 2018). "Surprisingly, sublethal infection with either Pmt2-expressing or Pmt2-deficient yeast cells did not change core body temperatures, despite the production of fever-inducing cytokines (e.g., tumor necrosis factor alpha [TNF-α], interleukin-1β [IL-1β], and IL-6) after infection." (PMID 29295913, 2018). "Notably, IL-1β is the best-characterized and most extensively studied pro-inflammatory cytokine in IL-1 family, and plays a vital role in host defense in response to infections and injuries." (PMID 30515160, 2018). "Because IL-1β and IL-18 are upregulated by caspase-1, caspase-1 may mediate additional mechanisms such as pyroptosis, which supports the importance of its regulation during infection." (PMID 29616195, 2018). "However, in vitro infection of mouse colonic epithelial CMT-93 cells by T. gondii PRU strain did not trigger inflammasome-associated IL-1β secretion." (PMID 29291748, 2018). "However IL-1β gene expression began to decrease post 8h infection with 16QsV." (PMID 30089163, 2018). "However, UPEC strains induced higher IL-1β release compared to MG1655, indicating that IL-1β could be beneficial for the bacteria and the progression of the infection." (PMID 29662840, 2018). "We found that IL-1β and IL-18 mRNA, as well as protein levels of mature IL-1β (p17) and cleaved fragment of pro-caspase-1 (p10) were significantly increased at 18 h post infection (p.i.), suggesting that inflammasome signaling was activated at early stage of YM infection." (PMID 30470758, 2018). "Infection of ZIKV progressively damaged mouse testes, increased testicular oxidative stress as indicated by the levels of reactive oxygen species, nitric oxide, glutathione peroxidase 4, spermatogenesis-associated-18 homolog in sperm and pro-inflammatory cytokines including IL-1β, IL-6, and G-CSF." (PMID 29447264, 2018). "Cytokines, such as TNF, IFN-γ, IL-6 and IL-1β, are likely to be beneficial in the early stages of the infection in parasite clearance, but might actually contribute to the pathogenesis associated with CM, and to disease severity and death if produced in an unregulated manner." (PMID 30477519, 2018). "We suspect that HMGB1 and IL-1β bind in vesicles as they are packaged for secretion; however this needs to be elucidated further and we predict that MV/HMGB1 levels will correlate with poor patient outcome, increased immune dysfunction and infection susceptibility in a large cohort of patients." (PMID 29601597, 2018). "Interestingly, neutrophils seems to be more resistant to pyroptosis than macrophages in response to Salmonella and are able to maintain a sustained IL-1β production and secretion, which could be important to control the infection." (PMID 30459758, 2018). "However, it may be due to higher levels of expression or activity of P2 receptors, which is correlated with eATP triggered increases in the levels of ROS, NO, IL-1β, and CC chemokine ligand-2 in intracellular infections in comparison with uninfected cells." (PMID 30038612, 2018). "SFB in Tac B6 mice of our study persistently and predominantly colonized the ileum irrespective of infection status, which was associated with over 100-fold increase of ileal Il-17A mRNA, but not Tnfα and Il-1β mRNA when compared to both H. pylori infected and control Jax mice." (PMID 29789574, 2018). "Moreover, the evaluation of IL-1β and IL-18 produced as a result of inflammasome activation is inadequate in revealing the significance of formed multiprotein platforms in the course of developing infection." (PMID 29348763, 2017).
infection (continued). "We also found a shift in colonization of H. suis from the pyloric gland zone during the more acute phase of the infection (2–3 months old pigs) to the fundic gland zone in the more chronic phase of the infection (adults sows) in combination with upregulated expressions of IL-8 and IL-1β." (PMID 28619040, 2017). "In chickens, activated macrophages produce a variety of pro-inflammatory cytokines, and modulation of the inflammatory reaction via the upregulation of a few inflammatory cytokines (IL-1β, IL-6, IL-8, and IL-18) might contribute to bursa lesions after vvIBDV infection." (PMID 28086922, 2017). "These analyses suggest that repeated insertions of dissolving or hydrogel-forming MN arrays do not stimulate the humoral immune system, do not produce sufficient trauma to elevate circulating blood levels of IL-1β and do not caused infection or trigger an inflammatory response cascade." (PMID 28478160, 2017). "Taken together, during priming or natural infection with Gram (+ve) or Gram (−ve) pathogenic or commensal bacteria, the UBE2L3 status of host cells sets the upper limit on the amount of pro-IL-1β substrate available for caspase-1 processing and thus controls mature IL-1β production." (PMID 28147281, 2017). "Meanwhile, 1 mM NaO may exert pro-inflammatory effects prior to infection, with respect to IL-1β gene expression and secretion as well as chemokine gene expression, but it can act as an anti-inflammatory after infection due to the IL-10 and IL-1β gene expression and the IL-1β secretion." (PMID 28361042, 2017). "To further investigate infection-induced alterations in inflammation, we detected the expression of inflammatory factors, such as tumour necrosis factor α (tnfα), il-8 and il-1b, during the early stage of infection, which could activate and induce neutrophil translocation to the infection site." (PMID 28835569, 2017). "Hence, apart from macrophages, neutrophils and NK cells, our results suggested that virus-infected neuronal cells may also up-regulate IL-1β to recruit immune cells, including NK cells, to the site of infection, and to trigger IFN-γ production." (PMID 28724943, 2017). "After the infection of untransfected and hBD-2- or hBD-3-transfected Caco-2 cells with E. faecium and/or S. typhimurium, we examined the host response by evaluating the expression of proinflammatory cytokines IL-6, IL-8 Il-1α, and IL-1β and anti-inflammatory cytokine TGF-β by real-time PCR." (PMID 29250559, 2017). "The negative regulator of IL-1β, IL-1Ra was induced by L. (V. ) brazilienis, however this induction was not affected by IL-32γ levels, thus suggesting that IL-32γ is dispensable for IL-1β production but can enhance the effects of IL-1β during L. (V. ) braziliensis infection." (PMID 28241012, 2017). "Therefore, when DC (or macrophages) are confronted with non-invasive yeast, they can clear the infection by rapid phagocytosis, especially macrophages, and limited production of IL-1β, and hence in the case of mDC, which respond to autocrine and macrophage-derived IL-1β IL-6 and IL-23." (PMID 28736555, 2017). "Stronger stimuli, such as intracellular infections with gram-negative bacteria could instead induce pyroptosis, causing massive release of IL-1β and possibly DAMPs, and dysregulated cytokine production." (PMID 28421072, 2017). "Interestingly, the trend towards increased IL-1β protein expression observed in the hippocampus on day 5 to 7 postPbA infection in WT mice was not present in ST2 deficient mice." (PMID 28448579, 2017). "By combining in vitro infection and transwell co-culture models with a global transcriptomic approach, we identified PBECs to be inert to direct Mtb-infection, yet to be potent responders within an Mtb-activated immune network, mediated by IL1β and type I interferon (IFN)." (PMID 28863187, 2017).
infection (continued). "Data from studies of infection with L. monocytogenes in mice indicate that treatment with hLf displayed significant effects on one main organ target of this pathogen in regards to bacterial colonization, necrosis, and mRNA expression of pro-inflammatory cytokines TNFα, IL-1β and IFNγ." (PMID 28257033, 2017). "However, the involvement of this cytokine for the establishment of antimicrobial defense mechanisms via induction of trained immunity is supported by studies showing that injection of IL-1β before infection can protect against infection with Pseudomonas aeruginosa or Candida albicans." (PMID 28951586, 2017). "Additionally, 46 genes encoding for secreted proteins may serve as markers in blood for the degree of protection (Cxcl9, Gp2, and Pla2g2d), intensity of infection (Retnla, Saa3, Il6, and Il1b), or adaptive recall responses (Ighg, C1qb)." (PMID 28243609, 2017). "In EBOV-infected patients, fatal infection was associated with high levels of IL-10 and IL-1RA, modest levels of TNF-α and IL-6, and non-detectable levels of IL-1β, MIP-1α, and MIP-1β, while survivors were characterized by high levels of TNF-α, IL-1β, and IL-6 in plasma." (PMID 28861075, 2017). "To gain further insight into the role of neutrophil-derived il1β on granuloma formation, we investigated whether targeted knockout of caspase b, which should result in a reduction of processed il1β, would result in impaired macrophage recruitment to sites of infection." (PMID 28747644, 2017). "A steady state increased level of IL-1β detected in all adjuvant immunized animals as compared to naive animals (untreated mice) points to the activation of innate responses, which is a pre-requisite of any effective acquired immune responses generated by infection or vaccination." (PMID 28955328, 2017). "Similarly, in vitro infection of mouse bone marrow cells with highly pathogenic M. tuberculosis Beijing led to a stronger induction of expression of genes for the proinflammatory cytokines IL-1β, IL-12, and TNFα than did infection of cells with less virulent mycobacterial strains." (PMID 27066505, 2016). "The proinflammatory cytokines, such as IL-1β and IL-6, play essential roles on the initiation and propagation of inflammatory response, whose level in upper genital tract were increased with the pathogen infection and the recognition of immunogens by local TLRs." (PMID 27887650, 2016). "However, because some cytokines such as IL-1β, IL-6, or IL-10 typically produced during infection are known to alter DC differentiation, indirect mechanisms might be of similar importance." (PMID 26870700, 2016). "As Il1b-/- mice did not develop infection or mucosal inflammation, and proinflammatory genes were not expressed, the IL-1β response may help render the bladder mucosa susceptible to infection, possibly by enhancing bacterial growth or tissue invasion." (PMID 27732661, 2016). "Besides chemokines, cytokines such as TNF-α are released acutely in response to injury or infection, and function to initiate and maintain the inflammatory process in part by stimulating other pro-inflammatory cytokines (e.g., IL-1α, IL-1β, and IL-6) and chemokines (e.g., CCL2, CCL3, and CXCL2)." (PMID 26860080, 2016). "However, we found higher expression of IL-1β mRNA in WT mice at 12 and 16 weeks of infection." (PMID 27056545, 2016). "In this study, significant increase in the levels of pro-inflammatory type 1 (TNF-α, IFN-γ, IL-6, IL-1β), pro-inflammatory type 2 (IL-33) and anti-inflammatory type 2 cytokines was observed in unimmunized mice after bacterial challenge indicating the spread of infection." (PMID 26904021, 2016). "Indeed, our subsequent gene expression analyses revealed us that IL-1β was in fact significantly up regulated in the susceptible D2 parental strains compared to B6; also, there was a significant correlation between infection severity (as measured by survival index) and IL-1β expression levels." (PMID 27399650, 2016).